ZNF341 (zinc finger protein 341)
Description:
Transcriptional activator of STAT3 involved in the regulation of immune homeostasis. Also able to activate STAT1 transcription.
Synonyms: dJ553F4.3; HIES3
Tractability: No criterion of Open Targets' tractability assessment is met for any kind of drug.
Gene: Protein-coding gene on chromosome 20 (33,731,657 to 33,792,269, forward strand). Ensembl gene ENSG00000131061.
Subcellular location: Nucleus
Subcellular location (Human Protein Atlas): Nucleoplasm; Vesicles; Nuclear bodies
Gene Ontology:
Molecular function: DNA binding; DNA-binding transcription activator activity; protein binding; DNA-binding transcription factor activity, RNA polymerase II-specific; RNA polymerase II cis-regulatory region sequence-specific DNA binding; DNA-binding transcription factor activity
Biological process: regulation of DNA-templated transcription; positive regulation of DNA-templated transcription; regulation of transcription by RNA polymerase II
Cellular component: nucleus
Genetic constraint (gnomAD): Loss-of-function variants: 52 observed, 86.67 expected, observed/expected ratio (o/e) 0.6, 90% interval 0.48 to 0.76. The upper end of that interval is the gene's LOEUF score, 0.76, which puts it in group 3 of 6, group 1 being the genes least tolerant of losing a copy. Missense variants: 977 observed, 1,141.7 expected, observed/expected ratio (o/e) 0.86, 90% interval 0.81 to 0.9. Synonymous variants: 459 observed, 478.25 expected, observed/expected ratio (o/e) 0.96, 90% interval 0.89 to 1.04.
Gene-disease validity (ClinGen):
ClinGen rates the evidence that ZNF341 causes each of these diseases.
hyper-IgE recurrent infection syndrome 3, autosomal recessive (autosomal recessive): Definitive. A rare hyper-IgE syndrome characterized by atopic dermatitis (eczema), chronic mucocutaneous candidiasis, and elevated IgE levels due to ZNF341 deficiency.
Homologues: Orthologues: chimpanzee ZNF341 (99% identical), macaque ZNF341 (97% identical), dog ZNF341 (96% identical), pig ZNF341 (94% identical), guinea pig ZNF341 (92% identical), rabbit ZNF341 (90% identical), mouse Zfp341 (90% identical), rat Zfp341 (89% identical), tropical clawed frog znf341 (59% identical), zebrafish znf341 (53% identical), Drosophila melanogaster M1BP (11% identical), Drosophila melanogaster CG1792 (10% identical), and 4 more.
Diseases named in the same sentence as ZNF341 in open-access papers:
ZNF341 is named in the same sentence as 13 diseases in open-access papers, as found by Europe PMC text mining. Sharing a sentence is not in itself a finding about the gene and the disease. The quoted sentences say what the papers report.
hyper-IgE syndrome (3 papers, 2023 to 2025). A condition that is characterized by elevated serum IgE, dermatitis, and respiratory infections. "Therefore, biallelic ZNF341 LOF mutations are considered as an autosomal recessive cause of hyper-IgE syndrome (HIES)." (PMID 37140667, 2023).
atopic dermatitis (1 paper, 2025). "Other HIES: As a result of dupilumab administration, significant clinical improvement and reduced IgE level were reported in a ZNF341 deficient adult patient with severe atopic dermatitis." (PMID 39945219, 2025).
breast carcinoma (1 paper, 2021). "High expression of ZNF644 might be associated with the radiosensitivity of breast cancer patients, and reciprocally, low expression of the other 3 genes (ZNF341, ZNF544, and ZNF653) marked patients in the radiosensitive group." (PMID 34504527, 2021). "Multivariate Cox regression analysis of the two databases showed that high expression of ZNF644 and low expression of ZNF341, ZNF541, and ZNF653 were associated with radiosensitivity of breast cancer." (PMID 34504527, 2021). "High expression of ZNF644 and low expression levels of the other 3 genes (ZNF341, ZNF541, and ZNF653) were related to the radiosensitivity of breast cancer." (PMID 34504527, 2021).
colon cancer (1 paper, 2025). "Although we do not have definitive evidence or validation of the role of ZNF341 in the colon cancer subtypes, we believe that this suggestive result demonstrates how multiomic network analysis can find complex regulatory patterns." (PMID 41114645, 2025).
dermatitis (1 paper, 2025). An inflammatory process affecting the skin. "The hyper-IgE phenotype and clinical features of atopic disease, like dermatitis, food allergy, and eosinophilia, seen in STAT3 deficiency and ZNF341 deficiency are replicated by pathogenic variants in IL6R or IL6ST." (PMID 40040707, 2025). "Currently, there is a lack of correlation between ZNF341 deficiency and common atopic symptoms such as asthma, dermatitis, rhinitis, and food allergies." (PMID 40040707, 2025).
Immunodeficiency (1 paper, 2025). Failure of the immune system to protect the body adequately from infection, due to the absence or insufficiency of some component process or substance. "The latest IUIS classification has redefined DOCK8 deficiency as a combined immunodeficiency, and other genes like ZNF341 and components of the IL-6 pathway (IL6ST, IL6R) can cause HIES-like phenotypes." (PMID 41458089, 2025).
primary immunodeficiencies (1 paper, 2022). "There was an increase in overall cancer incidence among patients with primary immunodeficiencies of ZNF341." (PMID 35057823, 2022).
cancer (2 papers, 2022). A tumor composed of atypical neoplastic, often pleomorphic cells that invade other tissues. "Specificity protein 1 (SP1) is associated with different types of cancer, neurological and cardiovascular disease and ZNF341 is involved in immune-mediated disorders and infection susceptibility by regulating IL-6 signaling." (PMID 36266402, 2022).
infection (2 papers, 2022 to 2025). The state of being infected such as from the introduction of a foreign agent such as serum, vaccine, antigenic substance or organism. "Similarly, a notable decrease in the exon-containing isoform of the znf341 gene was observed following 36 h of infection with V. harveyi." (PMID 41465195, 2025).
ZNF341 also shares sentences with these, for which no sentence is quoted: autoimmune polyendocrine syndrome type 1 (1 paper); chronic mucocutaneous candidiasis (1); food allergy (1); genetic disorders (1).